GRM3 (glutamate metabotropic receptor 3)
Diseases named in the same sentence as GRM3 in open-access papers (continued):
Sharing a sentence is not in itself a finding about the gene and the disease.
psychosis (8 papers, 2011 to 2025). "To evaluate the association between GRM3 and methamphetamine-induced psychosis, we conducted a case-control study of Japanese samples (181 methamphetamine-induced psychosis and 232 controls)." (PMID 21886583, 2011). "To evaluate the association between GRM3 and methamphetamine-induced psychosis, we conducted a case-control study of Japanese samples (181 methamphetamine-induced psychosis patients and 232 controls)." (PMID 21886583, 2011). "Among the 170 propsychotic target genes, 8 were a high-confidence psychosis risk gene (GRIN2A, DRD2, CYP2D6, CHRNB4, CHRM4, GABBR1, GRM3, CHRNA3)." (PMID 40701976, 2025). "This suggests that mGluR3 gene (GRM3) is a good candidate gene for the pathogenesis of methamphetamine-induced psychosis." (PMID 21886583, 2011). "We performed an association study of rs6465084 in GRM3 and METH- induced psychosis in the Japanese population." (PMID 21886583, 2011). "Since the symptoms of methamphetamine-induced psychosis are similar to those of paranoid type schizophrenia, it would seem that the mGluR3 gene (GRM3) is a good candidate gene for the pathogenesis of methamphetamine-induced psychosis." (PMID 21886583, 2011). "We did not detect an association between rs6465084 in GRM3 and Japanese methamphetamine-induced psychosis." (PMID 21886583, 2011). "Our findings suggest that rs6465084 in GRM3 does not play a major role in the pathophysiology of methamphetamine-induced psychosis in the Japanese population." (PMID 21886583, 2011). "This influence of GRM3 on prefrontal cortex and cognitive function suggests that abnormalities in glutamate neurotransmission may be involved in the pathophysiology of METH- induced psychosis." (PMID 21886583, 2011). "Our results suggest that rs6465084 in GRM3 does might not play a role in the pathophysiology of METH-induced psychosis in the Japanese population." (PMID 21886583, 2011). "However, we did not detect an association between GRM3 and METH-induced psychosis." (PMID 21886583, 2011).
Anxiety (6 papers, 2015 to 2025). Intense feelings of nervousness, tension, or panic often arise in response to interpersonal stresses. "It is also worth noting that we did see some phenotypic differences in the GRM3−/− mice on the anxiety tests." (PMID 25158312, 2015). "Furthermore, the anxiolytic effects of the group II agonists are absent or reduced in single GRM2−/− and GRM3−/− mice, confirming that the drugs are indeed acting through both of the group II metabotropic glutamate receptor subtypes to reduce anxiety." (PMID 25158312, 2015). "Similarly, no consistent differences in anxiety-like behaviours were evident between either GRM2−/− or GRM3−/− mice, and their respective controls." (PMID 25158312, 2015).
Alzheimer disease (5 papers, 2017 to 2025). A progressive, neurodegenerative disease characterized by loss of function and death of nerve cells in several areas of the brain leading to loss of cognitive function such as memory and language.
autism (5 papers, 2017 to 2024). Persistent deficits in social interaction and communication and interaction as well as a markedly restricted repertoire of activity and interest as well as repetitive patterns of behavior. "Cells in the later pseudotime stage exhibited specific enrichment in synaptic pathways, characterized by the upregulation of several neuronal markers, including CUX2, glutamate metabotropic receptor genes (GRM1, GRM2, and GRM3), and several autism risk genes, including PTEN, SCN2A, and SHANK2." (PMID 39363111, 2024). "Intriguingly, research indicating miR-10a-5p’s involvement in the pathogenesis of autism by modulating Grm3 expression further supports its role as a critical neuroprotective agent in mental health disorders." (PMID 39588356, 2024). "Our data indicate that expressions of BDNF, Grm3, Foxp1, Auts2 and Shanks3 in the hippocampus are significantly induced by L-serine administration in GHRH-KO mice via changed expression of epigenetic markers, which may ameliorate impairment of memory and autism-related behavior." (PMID 36672612, 2022).
alcohol dependence (2 papers, 2012 to 2022). Physical and psychological dependence on alcohol. "Our rationale for studying GRM3 in alcoholism is based on this SNP's involvement in other neuro-psychiatric diseases." (PMID 22909248, 2012). "Several animal studies have looked at the influence of GRM3 activation on alcohol dependence and addiction to other drugs." (PMID 22909248, 2012). "The effect of GRM3 SNPs on alcoholism has not been reported to our knowledge, therefore there are not specific studies regarding this." (PMID 22909248, 2012).
breast tumor (2 papers, 2017 to 2022). "Although we have not been able to demonstrate any clear connection between extracellular glutamate and breast tumour cell growth or resistance to apoptosis, we find that the GRM3 metabotropic glutamate receptor is intimately linked to invasive behaviour." (PMID 29269878, 2017).
colon cancer (2 papers, 2023 to 2025). "GRM3 plays important roles in colon cancer pathogenesis and knockdown of GRM3 in colon cancer cells reduced tumor cell survival in vitro and inhibited tumor growth in vivo." (PMID 36671500, 2023).
chronic myelogenous leukaemia (1 paper, 2020). "PE‐Ima (LIF, MRGPRF, GRM3, TNNI1 and CACNA2D1) predicted imatinib response in chronic myelogenous leukaemia patients." (PMID 34766125, 2020).
Cirrhosis (1 paper, 2026). A chronic disorder of the liver in which liver tissue becomes scarred and is partially replaced by regenerative nodules and fibrotic tissue resulting in loss of liver function. "We found that mRNA expression of mGluR3 (Grm3) was upregulated in HCC, while the protein level was significantly increased from the cirrhosis stage, and even more in HCC." (PMID 42123462, 2026).
heroin dependence (1 paper, 2014). Physical and psychological dependence on the drug heroin. "Also, we failed to obtain the findings on the relationship between GRM3 polymorphisms and heroin dependence from other genetic association studies." (PMID 24498053, 2014).
lung adenocarcinoma (1 paper, 2020). A carcinoma that arises from the lung and is characterized by the presence of malignant glandular epithelial cells. "Moreover, considering the frequent alterations of THSD7B, SYNE2, GRM3, and FLNC in lung squamous cell carcinoma and lung adenocarcinoma, we investigated the applicability of ITS to NSCLC patients treated with ICIs." (PMID 32969604, 2020).
Obesity (1 paper, 2025). Accumulation of substantial excess body fat. "Taken together, our study identify Raptin as a unique hypothalamic hormone that cooperates with GRM3 to suppress appetite and obesity, thus providing a potential new avenue to treat obesity." (PMID 39875551, 2025).
Squamous non-small cell lung cancer (1 paper, 2021). "Squamous non-small cell lung cancer (NSCLC), adenocarcinomas, and melanomas have all been linked to mutations in the glutamate receptors GRM8, GRM1, and GRM3." (PMID 34943797, 2021).
thyroid cancer (1 paper, 2013). "The present study reports for the first time the mutational status of the GNA11, MMP27, FGD1, TRRAP and GRM3 genes in thyroid cancer." (PMID 24137342, 2013). "The mutation status in the GNA11, MMP27, FGD1, TRRAP and GRM3 genes has not been studied in thyroid cancer." (PMID 24137342, 2013). "No GRM3 mutations were detected in 12 thyroid cancer cell lines." (PMID 24137342, 2013). "This suggests that TRRAP and GRM3 may not have important roles in the pathogenesis of this type of thyroid cancer." (PMID 24137342, 2013). "In conclusion, the present findings suggested that genetic alterations in the GNA11, MMP27, FGD1, TRRAP and GRM3 genes may not be significant in the tumorigenesis of thyroid cancer." (PMID 24137342, 2013).
tumor (21 papers, 2017 to 2026). "GRM3 and NF1 were mutated at 38% and 21%, respectively, with mutations distributed along the gene coding regions, consistent with their tumor suppressor nature." (PMID 30312528, 2019). "We tested the involvement of GRM3 in invasive responses by generating MMTV-PyMT tumour-derived cells in which GRM3 expression is disrupted by CRISPR gene editing (CRISPR-GRM3)." (PMID 29269878, 2017). "GRM3 is the only member of the group II receptor subclass expressed by MMTV-PyMT tumour-derived cell lines and MDA-MB-231 cells." (PMID 29269878, 2017). "Inhibition of GRM3 with LY95 significantly opposed the ability of MMTV-PyMT tumour-derived cell lines and MDA-MB-231 cells to invade this 3D microenvironment." (PMID 29269878, 2017). "For instance, glutamate signaling was reported to promote tumor-derived exosome formation, in which extracellular glutamate (Glu) transported by the Xc system activated glutamate metabotropic receptor 3 (GRM3) to positively regulate Rab27-mediated exosome production." (PMID 39598562, 2024). "In addition, we observed that tumours with RS4 had an increased frequency of SVs in genomic regions containing MDM2, H3F3B, PTPRB and GRM3 compared to tumours devoid of RS4." (PMID 35396535, 2022). "Furthermore, disruption of GRM3 using CRISPR significantly opposed the ability of MMTV-PyMT tumour-derived cells to invade into organotypic plugs, and this was completely rescued by expression of flag-tagged human GRM3." (PMID 29269878, 2017). "PCA-based characterization of two cell lines revealed that the increased motility and invasion in TMD cells, tumor-derived cells, than BMD cells, harvested from bone metastasis, was linked to the elevated expression level of S100A4 calcium-binding protein and functionality of GRM3." (PMID 28615627, 2017). "The expression of mGluR1 (GRM1) and mGluR5 (GRM5) was conserved from primary tumours to metastatic samples, but moderate changes were evident for other receptors such as mGluR2/3/7/8 (GRM2, GRM3, GRM7, and GRM8)." (PMID 37173906, 2023). "Our results are in line with previous reports, showing that high GRM3 expression in GBM patients correlates with poorer survival and limited tumor-free survival." (PMID 34290229, 2021). "Finally, we validated our findings in our novel human organotypic section-based tumor model, where GBM growth and proliferation was significantly reduced when GRM3 inhibition was combined with temozolomide application." (PMID 34290229, 2021). "Considering that GSCs give rise to faster cycling bulk tumor cells, we further speculate that the observed moderate in vitro inhibition of GSC self-renewal by Grm3 inhibition may still exert relevant long-term effects on overall tumor growth." (PMID 33575479, 2021). "Pharmacologic inhibition of Grm3 signaling utilizing two members of a novel class of negative allosteric modulators of Grm3 signaling inhibited self-renewal, GSC marker expression, and in vivo tumor growth in one of two GSC xenograft models." (PMID 33575479, 2021).
psychiatric disorder (11 papers, 2008 to 2025). A disorder characterized by behavioral and/or psychological abnormalities, often accompanied by physical symptoms. "We selected GRM3 as a proof-of-concept target due to its known epigenetic relevance in mental illness." (PMID 40559449, 2025). "Group II metabotropic glutamate receptors (mGluR2 and mGluR3, also called mGlu2 and mGlu3, encoded by GRM2 and GRM3, respectively) are therapeutic targets for several psychiatric disorders." (PMID 18720515, 2008).
cancer (7 papers, 2013 to 2022). A tumor composed of atypical neoplastic, often pleomorphic cells that invade other tissues. "Besides alterations in these cancer hallmark genes, SNVs were identified in the less characterized genes GRM3, MST1R, PRKN, and PIK3C2G." (PMID 34399808, 2021). "We identified 35 genes that were more frequently altered in HS/CB tumors versus corresponding TCGA cohorts; of which, 8 genes (PREX2, BIRC6, CNTNAP2, PTPRB, GRM3, ANKRD11, BRCA2, and TET3) are listed on the OncoKB Cancer Genes catalogue." (PMID 34446728, 2021). "Our results showed that the heat diffusion algorithm predicted 5 putative cancer gene CDH10, CHST11, GRM3, VAV1 and CCR4 from Tier 2 of the Cancer Gene Census6." (PMID 31500564, 2019). "In SCLC, it can be observed that cancer gene alterations appear to be more frequent in women, the most consistent differences being observed in PTRD, CREBBP, GRM3, ATRX, NOTCH3, and PDE4DIP, while ATM appears to be altered in 5.26% of men, and no alterations were depicted in women." (PMID 35330454, 2022).
neurological diseases (2 papers, 2011 to 2021). "The downregulated genes include one encoding a protein that interacts with amyloid-β precursor protein (ANKS1B) and two encoding glutamate receptors (GRIA2, GRM3), suggesting changes in astrocytic responses to synaptic glutamate release in multiple neurological disorders." (PMID 34172753, 2021).
adenocarcinoma (1 paper, 2023). A common cancer characterized by the presence of malignant glandular cells. "The KMT2D, GNAS, EP300, GRM3, and PIK3CG mutations were all significantly higher in patients with squamous than those with adenocarcinoma (P = 0.0066, P = 0.019, P = 0.0075, P = 0.017, and P = 0.0075, respectively)." (PMID 37301854, 2023).
GRM3 also shares sentences with these, for which no sentence is quoted: cognitive disorder (4 papers); amyotrophic lateral sclerosis (3); ischemia (3); mental disorder (3); bone cancer (2); epileptic seizure (2); neurodegenerative disease (2); alcohol addiction (1); alcoholism (1); Cerebral ischemia (1); cocaine addiction (1); dementia (1); esophageal tumor (1); Hypertension (1); injury (1); intellectual disabilities (1); lung carcinoma (1); lung squamous cell carcinoma (1); malignant glioma (1); medulloblastoma (1); mucosal (1); multiple sclerosis (1); neuropathy (1); Parkinson disease (1); psychostimulant addiction (1); skin cancer (1).